CD1C (CD1c molecule)
Diseases named in the same sentence as CD1C in open-access papers (continued):
Sharing a sentence is not in itself a finding about the gene and the disease.
tumor (continued). "H-1299 tumor cells regulate the development of CD1c+ DC subsets derived from NSCLC patients mediated by CD205 and CD103." (PMID 31921114, 2019). "IL-27 produced by DCs is necessary for trafficking of Tregs to locate in tumor, and pulmonary CD1c+ DC-mediated development of Tregs is dependent on IL-27/IL-10/inducible costimulator ligand." (PMID 30483251, 2018). "Based on phenotype and gene expression analysis, we have identified the CD1c+ DC population found in tumor ascites as naturally-occurring mo-DCs12,13." (PMID 29967419, 2018). "Both CpG-C-stimulated pDCs and poly(I:C)-stimulated CD1c+ DCs enhanced the killing of K562 and Daudi tumor cells by autologous NK cells." (PMID 27853652, 2016). "In line with previous findings, we found that NK cells alone only induce minor killing of Daudi tumor cells, but culture of NK cells with poly(I:C)-activated CD1c+ DCs or CpG-C-activated pDCs enhanced their killing potential." (PMID 27853652, 2016). "This is likely the reason why LPS-stimulated CD1c+ DCs were unable to enhance IFN-γ production or tumor cell killing by autologous NK cells." (PMID 27853652, 2016). "Here, we investigated the non-polymorphic antigen presenting molecule, CD1c, that is only expressed on subsets of mature hematopoietic cells, as a potential immunotherapy target with reduced risk of off-tumor on-target toxicity in healthy tissues." (PMID 40777002, 2025). "We assessed the distribution pattern of myeloid subsets in the same manner as in our own data, and identified the enrichment of F13A1+ Mφ (OR = 1.60) and CD1C+ cDC2 (OR = 2.03) in multi‐primary tumours compared to solitary primary tumours and adjacent non‐tumour tissues." (PMID 39601163, 2024). "Furthermore, the expression levels of F13A1 and CD1C in myeloid cells were significantly higher in MPLC tumours than SPLC tumours." (PMID 39601163, 2024). "TIMELESS expression in LUAD tumor tissues was significantly negatively correlated with neutrophil biomarkers, dendritic cell biomarkers (HLA-DPB1, HLA-DQB1, HLA-DRA, HLA-DPA1, CD1C) and an immunophenoscore that predicted outcomes associated with the use of immune checkpoint inhibitors." (PMID 38261568, 2024). "We demonstrate conversion of CD5+/−CD1c+CD14− cDC2s to CD14+ cDC2s by tumor-associated factors, whereas monocytes failed to express CD1c under similar conditions." (PMID 38242119, 2024). "Moreover, CD1c+CD14+ cells show a defective stimulatory capacity of tumor antigen-specific CD8 T cell responses compared with CD1c+CD14− cells." (PMID 38242119, 2024). "However, we demonstrate that monocytes are incapable of transdifferentiating to CD1c+CD14+ DCs in response to tumor cues." (PMID 38242119, 2024). "To assess whether DCs and monocytes can give rise to tumor-induced CD1c+CD14+, we started in vitro differentiation assays with CD14− cDC2s or CD14+ monocytes isolated from HD PBMCs (purity ≥ 95%)." (PMID 38242119, 2024). "The correlation of CD1C expression with 50-star pathways in each tumor was analyzed using GSVA." (PMID 36755259, 2023). "In non-small cell lung cancer (NSCLC), the CD1c+ DCs subset may play an important role in anti-tumor immunity." (PMID 38099311, 2023). "Interestingly, the CXCL9+CD1C+ DCs cluster predominated over other clusters in the tumor tissue and was more likely to differentiate into LAMP3+ DCs, thus enhancing the immunosuppressive effect." (PMID 37187731, 2023). "Moreover, positive correlations were detected between CD1C expression and infiltration levels of CD4+ T and CD8+ T cells, indicating a key role of CD1C in regulating tumor immunology." (PMID 36755259, 2023). "Except for CD1C, other genes had lower mRNA levels in tumor tissues than in normal tissues." (PMID 37178414, 2023). "Similarly, Cd1c was expressed at low levels in tumor tissues, and LUAD patients with high gene expression of Cd1c survived longer." (PMID 34805160, 2021).
tumor (continued). "We have shown that targeting T cells against tumor-related lipid antigens presented by CD1c are a viable immunotherapy strategy for hematological malignancies, which are driven by the pathological counterpart of the cells that normally express CD1 group 1 molecules." (PMID 34381053, 2021). "However, even when the heterogeneity of CD1c+ cells is appreciated, including recruitment of CD14+CD1c+ DCs in tumor-draining lymph nodes, little is known about the function of CD1c+ subtypes." (PMID 32610077, 2020). "IT injection of the IgG1 monoclonal antibodies ipilimumab and avelumab may induce antibody-dependent cellular cytotoxicity, thereby enhancing the release of tumor antigens that can be captured and processed by CD1c (BDCA-1)+ myDCs." (PMID 33182610, 2020). "Bulk RNA-seq analysis of CD1c+CD14+ cells sorted from tumor-invaded lymph nodes indicated that they displayed a similar expression profile as blood DC3s (high expression of cDC2 markers such as CLEC10A and FCER1A combined with low expression of monocyte-associated markers such as C5AR1 and SOD2)." (PMID 32610077, 2020). "Our results suggest that NSCLC cells may induce immune tolerogenic DCs through modulating the expression and production of signal molecules and cytokines in CD1c+ DCs, which play an important role in anti-tumor immunity and immune tolerance in vivo." (PMID 31921114, 2019). "In agreement with the individual patient trajectories, the global trajectory defines the lower root initial state as being comprised of monocytes primarily from normal tissue, and the cell fate branches as comprising predominantly of tumor‐derived differentiated cells (M2 macrophages or CD1c+ DC)." (PMID 31033233, 2019). "We proposed that H-1299 tumor cells may also regulate the differentiation of CD1c+ DC subsets isolated from NSCLC patients." (PMID 31921114, 2019). "Both CD1c+ DCs and pDCs could enhance NK cell cytotoxicity, and interestingly DC co-cultures further enhanced NK cell-mediated killing of an NK-resistant tumor cell line." (PMID 27853652, 2016). "In another recent trial using CD1c+ mDCs, three out of 14 vaccinated metastatic melanoma patients showed functional tumor-specific T cells in peripheral blood and post-treatment skin tests, coinciding with improved progression-free survival and objective clinical responses." (PMID 28536413, 2015). "This study suggests that autoreactive CD1c-restricted T cells may play a role in anti-tumor immunity." (PMID 26175733, 2015). "This implies that CD1C may participate in CD8+T cell-mediated anti-tumor immunity." (PMID 36755259, 2023). "In NSCLC, CD1C+ DCs subsets may play vital roles in anti-tumor immunity." (PMID 36755259, 2023). "We obtained results on the correlation between TPPP3 expression and marker genes of tumor infiltration-associated immune cells, including CD8+T cells (CD8A and CD8B), B cell (CD19 and CD79a), and Myeloid dendritic cell (HLA-DPB1, HLA-DQB1, HLA-DRA, HLA-DPA1, CD1C, NRP1, and ITGAX)." (PMID 33083464, 2020). "Consequently, Ag delivery to CD1c+ DCs may further enhance tumor‐specific CD4+ T‐cell responses, even though anti‐CLEC9A and anti‐DEC‐205 Abs promote CD4+ T‐cell responses similarly after uptake by CD141+ DCs." (PMID 32547743, 2020). "In addition, incubation with H-1299 tumor cells suppressed the development of the CD1c+CD205+CD103+ DC subset, but it facilitated the differentiation of the CD1c+CD205+CD103− DC subpopulation when compared with that of DCs that were not cocultured with H-1299 cells." (PMID 31921114, 2019). "Since NSCLC cells downregulate the production of IL-12 and IL-23 in CD1c+ DCs, tolerogenic CD1c+ DCs may block T cell-mediated anti-tumor immunity via suppressing the production of IL-12 and IL-23 by CD1c+ DCs, which are necessary for T cell activation in vivo." (PMID 31921114, 2019).
tumor (continued). "However, further data analysis suggested that the relative frequency (as percentage of all DCs) may be different between tissues, with pDCs being more frequent and CD1c+ mDCs being less frequent in tumor compared to distal lung tissue." (PMID 30774636, 2018). "However, whether the CD1c-positive cells depletion occurs during the initiation, promotion, or progression of the tumor calls needs further elucidation." (PMID 28331853, 2017). "Therefore, co-administration of properly matured pDCs and CD1c+ mDCs may induce even more potent anti-tumor responses than pDCs or mDCs alone." (PMID 28536413, 2015). "The results unequivocally demonstrated that CD1C and F13A1 were significantly up‐regulated in multiple primary tumours compared to single‐primary tumours." (PMID 39601163, 2024). "Together, this indicates cDC2s as direct pre-cursors of DC3-like CD1c+CD14+ DCs and provides insights into the importance and modulation of CD14+ DC3s in anti-tumor immune responses." (PMID 38242119, 2024). "Our work highlights the plasticity of DCs, provides insights in the development of DC3-like CD1c+CD14+ DCs with cDC2s as pre-cursor, and possibilities to modulate DCs for enhanced anti-tumor responses to improve cancer therapies outcomes." (PMID 38242119, 2024). "After characterizing CD1c+CD14+ cells in NSCLC, we directed our efforts to dissecting their development driven by tumor-derived factors." (PMID 38242119, 2024). "By analyzing CD1C gene expression of BRCA samples from TCGA, we found that CD1C levels in tumor tissues were markedly lower than in normal tissues." (PMID 36755259, 2023). "To explore the correlation between CD1C and the TME, we analyzed the relationship between the CD1C gene and immune, stromal, and ESTIMAE scores and tumor purity in pan cancer." (PMID 36755259, 2023). "The levels of CD1C were positively correlated with immune, stromal, as well as ESTIMATE scores, and negatively correlated with tumor purity." (PMID 36755259, 2023). "RESULTS: We observed that CD1c+ and DC-SIGN+ DCs were more numerous in SLNs with a larger tumor size." (PMID 35955602, 2022). "Furthermore, non-small cell lung cancer (NSCLC) cells modulate the development of human CD1c+ subsets mediated by CD103 and CD205 which trigger the induction of tolerogenic CD1c+ DCs and the expansion of an immune suppressive microenvironment that causes tumor cells to escape immune surveillance." (PMID 36291050, 2022). "CD1a+ cells at tumor edge correlated with DC-LAMP+ (R = 0.64, p < 0.001) and CD1c+ cells (R = 0.33, p < 0.010) at the same location." (PMID 35955602, 2022). "In the mDCs group, CD1C+ mDC (CD1C, FCER1A, and CLEC10A) were reduced in the tumor compartment compared to the adjacent kidney." (PMID 36180422, 2022). "When micro- and macrometastatic SLNs were compared, we found significantly higher densities of CD1c+ and DC-SIGN+ DCs at tumor margin of the latter (U Mann–Whitney test: p < 0.003 and p < 0.035, respectively)." (PMID 35955602, 2022). "To sum up, we conclude that CD1a+ DCs show protective activity against cancer progression while CD1c+, DC-LAMP+ and DC-SIGN+ subsets favor tumor spread." (PMID 35955602, 2022). "Further, data in the GEPIA database were verified, and results confirmed the low expression of BTK and Cd1c in LUAD tumor tissues, and the finding that patients with high expression of BTK or Cd1c survived longer." (PMID 34805160, 2021). "The six genes of the signature belonged to different functional immune-related groups: antigen presentation (HLA-DPA1 and CD1C), innate immune response (TLR7), type II interferon signaling (IFNB1), tumor marker (MMP2), and proliferation marker (MKI67)." (PMID 34209514, 2021). "The six genes belonged to different functional groups: antigen presentation (HLA-DPA1 and CD1C), innate immune response (TLR7), type II interferon signaling (IFNB1), tumor marker (MMP2), and proliferation marker (MKI67)." (PMID 34209514, 2021).
tumor (continued). "High LPAR6 expression relates to a high infiltration level of DCs in the tumor tissue of LUAD patients, DC markers such as HLA-DQB1, CD1C and NRP1 show significant correlations with LPAR6 expression both in the tumor tissue in LUAD." (PMID 34769557, 2021). "Despite expression of CD1c on APC, tumor-reactive T cells differentially recognized CD1c-restricted mLPA presented by tumor cells, suggesting that CD1c-restricted lipid antigens specifically accumulate in malignant cells but not normal APCs." (PMID 33262761, 2020). "In humans, cDC2s are best aligned with the CD1c+ (BDCA1+) subset found in the blood and various tissues including tumor and comprise at least two subset populations as revealed by recent single-cell RNA-sequencing analysis." (PMID 31402908, 2019). "For example, CD123+ pDCs were found to selectively express CCR2, CMKLR1, and CXCR3, receptors known to be involved in DC maturation, trafficking and recruitment at tumor sites whereas XCR1 and CX3CR1, were selectively expressed by CD141+ mDCs and CD1c+ mDCs." (PMID 29795118, 2018). "The role of Th17 responses in tumor immune responses is controversial and the activation of effector memory Th17 cells via combinatorial TLR stimulation of CD1c+ DC now requires consideration in this context." (PMID 28878767, 2017). "One recent study showed that CD1c+ B cell leukemia precursors are efficiently targeted and lysed by CD1c autoreactive T cells, highlighting a role of group 1 CD1-restrcited T cells in anti-tumor immunity." (PMID 26175733, 2015). "Multiplex immunofluorescence analysis revealed that TLR7 was significantly upregulated by IFNα therapy in cells expressing myeloid cell markers such as CD1c+, CD68+ and CD141+ and in XCR1+ cells, a marker specific for type I DCs in the tumor and the surrounding stroma." (PMID 39849091, 2025). "Of note, Zilionis and co-workers use the term “DC3” in NSCLC for mature tumor-infiltrating DCs lacking CD14 expression, which do not correspond to the tumor-induced CD1c+CD14+ cells described here." (PMID 38242119, 2024). "A distinct overexpression of CD1c, CD2, CD3, CD4, CD11c, CD14, CD20, CD44, CD56, CD105, CD146, and CD209 was identified in LCa patients compared to healthy controls, correlating positively with tumor presence." (PMID 38902710, 2024). "In the tumor microenvironment (TME), DC plays a crucial role, divided into plasmacytoid DC (pDC) and conventional (cDC) or myeloid DC (myDC), further categorized as CD141 (BDCA-3)+ or cDC1 and CD1c (BDCA-1)+ or cDC2." (PMID 38954010, 2024). "Additionally, we conducted an in‐depth assessment of CD1C and F13A1 expression levels on myeloid cells across four distinct groups and compared myeloid cells in tumour tissues from MPLCs and SPLCs." (PMID 39601163, 2024). "We observed decreased CD1c+CD14+ DC frequencies in patients within 10 weeks after NSCLC resection, supporting the hypothesis of a tumor-driven emergence of CD1c+CD14+ DCs." (PMID 38242119, 2024). "Mature LAMP3+ DCs were transformed from CD1C+ DC and CLEC9A+ DC sub‐clusters when exposure to tumour alloantigens, which may improve T cell cytotoxicity activities on tumour cells under anti‐PD‐L1 treatments." (PMID 36305631, 2022). "Several studies have shown that Vδ1+ γδ T cells recognize CD1c-phosphomycoketide, CD1d-α-GalCer, CD1d-sulfatide, R-phycoerythrin (PE), ephrin receptor A2 (EphA2), and MHC-related protein 1 (MR1) ligands, and play a crucial role for anti-tumor responses." (PMID 35880177, 2022). "DCs were further subdivided into cDC1 (cross-presenting dendritic cells; cluster 5 in Paratumor and cluster 11 in Tumor; CLEC9A+ and XCR1+), cDC2 (cluster 1 in Paratumor and cluster 1 in Tumor; CD1C+) and plasmacytoid DC (pDC; cluster 4 in Paratumor and cluster 13 in Tumor; LILRA4+ and IL3RA+)." (PMID 33429363, 2021).
tumor (continued). "cDCs can be further divided into CD1c (BDCA1)+ DCs (cDC2s), which are specialized in immune responses against bacterial and fungi, and CD141 (BDCA3)+ DCs (cDC1s), specialized in cross-presentation of tumor antigens to prime CD8 T cells." (PMID 33255895, 2020). "In contrast, CD103 expression on CD1c+ DCs incubated with primary NSCLC cells was downregulated compared with that on CD1c+ DCs without coculture with primary tumor cells." (PMID 31921114, 2019). "The experimental data showed that the protein expression of CD40, CD80, CD86, and HLA-DR on CD1c+ DCs was downregulated after co-culture with primary NSCLC cells compared with that on CD1c+ DCs that were not cocultured with tumor cells." (PMID 31921114, 2019). "Our results indicate that coculture with primary NSCLC cells downregulates the production of IL-6, IL-12, and IL-23 by CD1c+ DCs compared with that of CD1c+ DCs that are not cocultured with primary tumor cells." (PMID 31921114, 2019). "Our data show that coculture with H-1299 cells upregulated the expression of CD205 but downregulated the expression of CD103 on CD1c+ DCs compared with that of those on CD1c+ DCs that were not cocultured with H-1299 tumor cells." (PMID 31921114, 2019). "The protein expression of CD205 and CD103 on CD1c+ DCs treated with primary tumor cells or without incubation with primary NSCLC cells was detected by flow cytometry." (PMID 31921114, 2019). "Our results demonstrate that coculture with H-1299 tumor cells leads to the upregulation of IL-6, IL-10, and IL-27 production by CD1c+ DCs compared with that by CD1c+ DCs that were not cocultured with H-1299 cells." (PMID 31921114, 2019). "Our results demonstrated that the expression of CD40, CD80, CD86, and HLA-DR was downregulated after coculture with H-1299 tumor cells compared with that on CD1c+ DCs that were not incubated with H-1299 cells." (PMID 31921114, 2019). "The experimental data indicate that the expression of CD205 on CD1c+ DCs was increased after coculture with primary tumor cells compared with that on CD1c+ DCs without incubation with primary NSCLC cells." (PMID 31921114, 2019). "CD1c+ mDCs seem specialized in immunity against bacteria and fungi, whereas CD141+ mDCs are specialized in detection and uptake of necrotic cell debris of virally infected cells or tumor cells and cross-presentation of derived antigens to CD8+ T-cells." (PMID 30999964, 2019). "Specifically, CD1c+ mDCs and CD141+ mDCs can be activated by a distinct set of toll-like receptors (TLRs), and subsequently secrete large amounts of cytokines IFN-γ and IL-12 which allow the highly effective induction of CTLs and Th1 responses against tumor." (PMID 26959879, 2016). "This study showed higher mRNA levels of MHC-I for tumours that will not relapse after treatment and tumours that will recur have lower expression of CD1c, CD1e and MCP-1." (PMID 22919375, 2012). "CD1c was not expressed by any of the three MΦ differentiation types, which is consistent with the hypothesis that the CD1chi subsets detected in the tumor were DCs." (PMID 38322012, 2023). "The upregulation of CD1C, CD40, CD80, and CD86 on Bregs shown in our study indicated that Bregs might exhibit a strong ability of antigen presentation in the MPE immune microenvironment in vivo due to tumor antigen stimulation." (PMID 37432957, 2023). "In addition, the experimental data demonstrate that the production of TGF-β by CD1c+ DCs incubated with primary tumor cells is similar to that by CD1c+ DCs that are not cocultured with primary tumor cells." (PMID 31921114, 2019). "Since our results indicate that H-1299 tumor cells downregulate the expression of CD40, CD80, CD86, and HLA-DR on CD1c+ DCs isolated from healthy donors, we proposed that H-1299 cells may also block the expression of costimulatory molecules on CD1c+ DCs derived from NSCLC patients." (PMID 31921114, 2019).